PDE4D (phosphodiesterase 4D)
Diseases named in the same sentence as PDE4D in open-access papers (continued):
Sharing a sentence is not in itself a finding about the gene and the disease.
prostate carcinoma (continued). "The anti-proliferative effects of PDE4D silencing had been previously reported in other types of cancer including lung cancer and prostate cancer." (PMID 34062786, 2021). "In this study, we found that PDE4D is the only PDE4 subtype with highly upregulated expression in the chemo-resistant prostate cancer cells in comparison to the chemo-sensitive prostate cancer cells." (PMID 34066000, 2021). "In consistence, the knockdown of PDE4D with siRNA induced similar effects on proliferation of chemo-resistant prostate cancer cells." (PMID 34066000, 2021). "As cell invasion and migration play important roles in the progression of cancer metastasis, we examined impacts of PDE4D inhibition with Eggmanone on invasion and migration of the chemo-resistant prostate cancer cell in vitro." (PMID 34066000, 2021). "PDE4 consists of four subtypes, PDE4A, PDE4B, PDE4C and PDE4D, and is involved in several human malignancies including prostate cancer, leukemia, colon cancer and glioma." (PMID 34066000, 2021). "Lately, multiple genomics studies have identified the PDE4D gene as a putative genomic driver/suppressor gene of (prostate) cancer." (PMID 31275657, 2019). "Pharmacologic inhibition of PDE4D using small-molecule inhibitors induce tumor growth inhibition correlated to the SHH pathway in prostate cancer." (PMID 31772658, 2019). "In our previous work we identified expression differences of various long PDE4D isoforms in primary tumour material that were different for the prostate cancer specific TMRPSS2-ERG gene rearrangement." (PMID 31275657, 2019). "Although one study used the SB transposon system to identify PDE4D as a candidate prostate cancer gene in mice based on the transposon insertion site, only focal epithelial proliferation and hyperplasia in the prostate were observed." (PMID 29874846, 2018). "A number of the top genes identified in this study have previously been implicated in prostate cancer development and progression, Gleason grade, metastases and biochemical recurrence; including CANT1, FBP1, RRM2, POLE2, PDE4D, and ALDH1A3." (PMID 27980733, 2016). "Taken together, our findings highlight the potential of PDE4D isoforms to be promising new biomarkers and potential therapeutic targets for localized and advanced prostate cancer." (PMID 27683107, 2016). "Overall, our findings highlight the relevance of PDE4D as prostate cancer biomarker and potential drug target." (PMID 27683107, 2016). "We show that expression of PDE4D isoforms is consistently altered in primary human prostate cancer compared to benign tissue, with PDE4D7 being up-regulated while PDE4D5 and PDE4D9 are down-regulated." (PMID 27683107, 2016). "Separation of a range of prostate cancer models and xenografts into androgen sensitive and androgen independent categories showed that PDE4D isoforms were downregulated in the androgen independent prostate cancer models." (PMID 25680530, 2015). "The PDE subtype, PDE4D, belongs to the PDE4 subfamily, which includes the four isoforms, A, B, C and D. It has been demonstrated that PDE4D functions as a proliferation promoting factor in prostate cancer through the Sleeping Beauty transposon system." (PMID 25289091, 2014). "Furthermore, preclinical studies have demonstrated that PDE4D inhibitors can potentially restrict prostate cancer cell proliferation." (PMID 39202484, 2024). "However, recent studies have indicated that targeting PDE4D can be used for the treatment of ER positive breast cancer, prostate cancer, or hepatocellular carcinoma." (PMID 37775746, 2023). "In this study, we examined PDE4 expression in chemo-sensitive and chemo-resistant prostate cancer cells and identified PDE4D is only subtype of PDE4 that shows enhanced expression in chemo-resistant prostate cancer cells in comparison to chemo-sensitive prostate cancer cells." (PMID 34066000, 2021).
prostate carcinoma (continued). "While Eggmanone treatment or PDE4D knockdown with siRNA dramatically attenuated the proliferation of the chemo-resistant prostate cancer cells in the presence of sonic Hedgehog ligand, suggesting that Eggmanone overcomes prostate cancer cell chemo-resistance via sonic Hedgehog signaling." (PMID 34066000, 2021). "We and colleagues previously reported that Eggmanone can effectively blocked sonic Hedgehog signaling via PDE4D inhibition, and here our study suggests that that Eggmanone downregulated proliferation of the chemo-resistant prostate cancer cells via sonic Hedgehog signaling." (PMID 34066000, 2021). "Our investigation of the transcriptional dynamics of the PDE4D gene locus revealed a previously undescribed promoter switch involving the major contributors of PDE4D activity in normal prostate, namely the PDE4D5 and PDE4D9 long forms, as well as the prostate cancer-associated long isoform PDE4D7." (PMID 27683107, 2016). "Indeed, cAMP-degrading PDEs have been associated with several diseases in recent years, including stroke, acrodysostosis and COPD, and more recently, expression of a specific PDE4D isoform (PDE4D7) has been related to prostate cancer." (PMID 27683107, 2016). "However, the role of PDE4D7 in prostate cancer appears distinct from that of PDE4D." (PMID 40129976, 2025). "Additionally, certain isoforms of PDE4D exhibit contrasting functions in prostate cancer." (PMID 39202484, 2024). "PDE4D inhibitor Eggmanone was found to significantly decrease the invasion and proliferation of the chemo-resistant prostate cancer cells, and treatment with the combination of Eggmanone and docetaxel dramatically overcomes prostate cancer cell chemo-resistance." (PMID 34066000, 2021). "Thus, by complementing PDE4D7 with the two other prostate cancer-relevant PDE4D transcripts, namely, PDE4D5 and PDE4D9, we have formulated a more effective prognostic model that has potential for assessing the risk of disease progression before primary intervention in prostate cancer." (PMID 31275657, 2019). "For example, the use of selective PDE4D inhibitors, NVP-ABE171 and cilomilast, in prostate cancer, both in vitro and in vivo, promoted a decrease in cell proliferation." (PMID 40535773, 2025). "Two long PDE4D isoforms, PDE4D5 and PDE4D9, were found to be down-regulated in primary prostate cancer with expression continuing to decrease as the disease progresses to CRPC." (PMID 37830741, 2023). "We previously identified the long PDE4D isoform PDE4D7 as a key player in the development and progression of prostate cancer." (PMID 36612262, 2022). "Here we found that the expression of PDE4 subtype, PDE4D, is highly elevated in the chemo-resistant prostate cancer cells (DU145-TxR and PC3-TxR) in comparison to the chemo-sensitive prostate cancer cells (DU145 and PC3)." (PMID 34066000, 2021). "As new strategies for targeted pharmacological manipulation of specific PDE4D transcripts become available then PDE4D7 likely provides a promising future target in the treatment of primary and/or advanced prostate cancer." (PMID 26575822, 2015). "In addition, Western blotting study further confirmed that PDE4D protein expression was dramatically elevated in chemo-resistant DU145-TxR and PC3-TxR cells in contrast to chemo-sensitive DU145 and PC3 cells, implying that PDE4D expression may be associated with the prostate cancer chemo-resistance." (PMID 34066000, 2021). "Nevertheless, all the current studies of PDE4D in prostate cancer have focused on the non-chemo-resistant prostate cancer, and no PDE4D studies in the more-advanced chemo-resistant prostate cancer have been reported to date." (PMID 34066000, 2021). "Inhibition of PDE4D with a potent and selective PDED4 inhibitor, Eggmanone, effectively decreases the invasion and proliferation as well as induces cell death of the chemo-resistant prostate cancer cells (DU145-TxR and PC3-TxR)." (PMID 34066000, 2021).
prostate carcinoma (continued). "In addition, overexpression of PDE4D was reported in human CRPC prostate adenocarcinoma samples in comparation with benign prostatic hyperplasia samples, and knockdown or inhibition of PDE4D reduces the growth of both CRPC prostate cancer cells in vitro and in vivo." (PMID 34066000, 2021). "While these alterations seem to be independent of copy number alterations in the PDE4D locus and driven by AR and ERG binding, we also observed increased DNA methylation in the promoter region of PDE4D5, indicating a long lasting alteration of the isoform composition in prostate cancer tissues." (PMID 27683107, 2016).
acrodysostosis (23 papers, 2014 to 2025). Acrodysostosis (ACRDYS) is a rare primary bone dysplasia characterized by severe brachydactyly, peripheral dysostosis with facial dysostosis, nasal hypoplasia, and developmental delay. "A de novo PDE4D variant (c.671C>T; p.Thr224Ile) was identified in a cousin presenting with syndromic acrodysostosis." (PMID 41464128, 2025). "In this review, we will use the iPPSD nomenclature; specifically, we will use iPPSD4 to refer to acrodysostosis caused by mutations in PRKAR1A and iPPSD5 for acrodysostosis caused by mutations in PDE4D." (PMID 38983619, 2024). "Mutations in the 3′5′cyclic AMP (cAMP)-dependent protein kinase (PKA) type I regulatory subunit isoform α (RIα) and phosphodiesterase (PDE) PDE4D have both been implicated in impaired PKA regulation in acrodysostosis." (PMID 37808519, 2023). "The PDE4D encodes phosphodiesterase 4D and is linked to schizophrenia, psychosis, acrodysostosis, and neuroticism." (PMID 35089962, 2022). "Another model based on pde4d morphants also resembles the symptoms of LOF mutations in human PDE4D gene that cause acrodysostosis." (PMID 34490030, 2021). "The CNS deficiencies that are seen in acrodysostosis appear to be considerably more severe than those seen in Pde4d-/- or PDE4D5-D556A transgenic mice, affecting multiple aspects of cognition and memory." (PMID 32784895, 2020). "Mutations in PDE4D in humans predispose to acrodysostosis, associated with cognitive and behavioral deficits." (PMID 32784895, 2020). "In humans, a specific set of mutations in PDE4D cause acrodysostosis, a disorder that affects bone formation." (PMID 32784895, 2020). "Acrodysostosis mutations cluster in a specific region of the PDE4D protein that is essential for its dimerization and regulation by phosphorylation by PKA." (PMID 32784895, 2020). "IUGR has also been described in other iPPSD, such as acrodysostosis with mutations in PRKAR1A or PDE4D, and in patients with mutations in PDE3A." (PMID 29280743, 2017). "Here, we report on a novel autosomal dominantly inherited heterozygous PDE4D mutation in a multigenerational family with acrodysostosis that illustrates the clinical variability of this syndrome even within one family." (PMID 28515031, 2017). "Given the pivotal role of cAMP in intracellular signaling triggered by various membrane-impermeable hormones, it can be hypothesized that dysregulation of cAMP levels may underlie the acrodysostosis associated with PDE4D variations." (PMID 41464128, 2025). "For example, PDE4D was reported to be associated with asthma and acrodysostosis." (PMID 40872681, 2025). "In order to improve our understanding, it will be important to develop cell, tissue and organism level models of acrodysostosis as this will allow for the understanding of how iPPSD5 manifests in the affected tissues as well as the changes mutations cause in PDE4D and PRKAR1A activity." (PMID 38983619, 2024). "However, unlike PRMT7-related disorder, these are all autosomal dominant disorders caused by heterozygous variants in GNAS (PHP 1A and 1C), PRKAR1A and PDE4D (acrodysostosis), and/or 2q37 deletion resulting in loss of the HDAC4." (PMID 36399134, 2023). "Patients with acrodysostosis and PDE4D mutations also have significant intellectual disability." (PMID 32784895, 2020). "In addition, heterozygous mutations in PRKAR1A, which encodes the regulatory subunit of protein kinase A (PKA) and PDE4D, which encodes phosphodiesterase type 4, have been found in patients with acrodysostosis." (PMID 29280743, 2017). "In this article, we reported a very rare case of autosomal dominantly inherited acrodysostosis type 2 in a three-generational family caused by a novel mutation in the PDE4D gene illustrating the significant phenotypic variability of acrodysostosis and discuss differential diagnosis." (PMID 28515031, 2017). "The PRKAR1A gene and PDE4D gene have been found to be causative genes of acrodysostosis." (PMID 25075981, 2014).
acrodysostosis (continued). "The seemingly predominant role of long PDE4D isoforms in regulating neuroplasticity and cognition is further underlined by the association of mutations in PDE4D exons specific to long isoforms and the rare genetic disorder acrodysostosis, which is characterized by intellectual disability." (PMID 37306762, 2023). "PDE4D-related acrodysostosis includes acroscyphodysplasia, characterized by a typical knee appearance and a more severe prognosis." (PMID 41464128, 2025). "iPPSD4 and iPPSD5 are subtypes including acrodysostosis (ACRDYS) caused by PRKAR1A and PDE4D alterations, respectively." (PMID 33179219, 2021). "Although much remains to be learned about the CNS phenotypes of PDE4D-mutant acrodysostosis, the available data demonstrate the profound effects of PDE4D alterations in the CNS and thereby the essential role of PDE4D in CNS function in humans." (PMID 32784895, 2020). "Another type of acrodysostosis, which lacks hormone resistance (ACRDYS2 or iPPSD5, OMIM#6146139), is caused by mutations in the gene coding for phosphodiesterase 4D (PDE4D)." (PMID 29499646, 2018). "Since then, two distinct genetic and phenotypic subtypes of acrodysostosis have been differentiated: acrodysostosis type 1 resulting from defects in PRKAR1A, and acrodysostosis type 2 caused by mutations in PDE4D." (PMID 28515031, 2017). "Hormone resistances, usually PTH and/or TSH resistance, have been detected in about 60-70% of acrodysostosis patients with a PRKAR1A mutation and in 10-20% of cases with PDE4D mutations." (PMID 29280743, 2017). "Recently, genetic defects in cAMP-dependent protein kinase type 1-α regulatory subunit (PRKAR1A) and cAMP-specific phosphodiesterase 4D (PDE4D) were identified in patients with acrodysostosis by candidate gene analysis and exome sequencing respectively." (PMID 28515031, 2017). "This disease continuum may encompass both forms of acrodysostosis (caused by PRKAR1A and PDE4D variants), Albright hereditary osteodystrophy, and pseudohypoparathyroidism (caused by GNAS variants)." (PMID 40917827, 2025). "In terms of enrichment in the Jessen disease database, acrodysostosis (padjusted = 0.068) and dementia (padjusted = 0.068) were the most relevant diseases, involving PDE4D, Sortilin Related Receptor 1 (SORL1) and Parkin RBR E3 Ubiquitin Protein Ligase (PARK2) genes." (PMID 41473159, 2025). "Similarly, most patients with acrodysostosis and a mutation in PRKAR1A or PDE4D are born SGA5,13,15." (PMID 29959430, 2018). "TSH resistance is present in patients with acrodysostosis owing to PRKAR1A mutations but not in those with PDE4D mutations." (PMID 29959430, 2018). "Previous reports have suggested that the PDE4D gene may be responsible for ASD, representing a more severe form of skeletal dysplasia encompassing acrodysostosis." (PMID 40917827, 2025).
asthma (23 papers, 2009 to 2025). "Relatively high genetic prediction levels of MICB (OR = 0.9984; 95% CI, 0.9979–0.9989; p = 1.04 × 10−9) and PDE4D (OR = 0.9980; 95% CI, 0.9972–0.9987; p = 1.89 × 10−7) were observed to reduce the risk of asthma in children." (PMID 38730525, 2024). "It was reported that PDE4D was not only a susceptibility gene for asthma but also for ever-smokers who were associated with a reduced FEV1 level." (PMID 32234053, 2020). "Conversely, the user can enter the disease term ‘asthma’ and retrieve the associated targets for asthma including PDE4D." (PMID 27899665, 2017). "PDE4D (phosphodiesterase 4D) functions as a regulator of airway smooth muscle contractility and was identified as an asthma susceptibility gene, and PDE4 inhibitors have been developed as medications for asthma." (PMID 23829686, 2013). "Our rank-based genome-wide analysis revealed for the first time an association of RYR2 variants with asthma and replicated previously discovered PDE4D asthma gene across human populations." (PMID 23829686, 2013). "It is thus not surprising that recent genome-wide association study (GWAS) for asthma identified PDE4D as a highly plausible candidate gene." (PMID 21876611, 2011). "This study demonstrates the first attempt to explore the association of PDE4D genetic variations and response to asthma b2-agonists treatment in Caucasian children." (PMID 21876611, 2011). "Similarly, the overall score for the ‘PDE4D-Asthma’ association combines the genetic association data type score, the drug data type score and the text mining data type score." (PMID 27899665, 2017). "The indirect effects of MICB, PDE4D, and IL‐21 on childhood asthma via BMI were relatively modest, at 3.31%, 5.03%, and 3.43%, respectively." (PMID 38730525, 2024). "Asthma shows reduced methylation in the Phosphodiesterase 4D (PDE4D) promoter area, impacting ASMCs’ proliferation." (PMID 38891935, 2024). "These anti-asthma drugs present strong evidence for DCT-compounds as potential future drug candidates through computational demonstration to target PDE4D." (PMID 32185106, 2020). "These four pathways included the asthma-related cAMP signaling pathway as well as two possible targets, PDE4D and PDE4B, members of phosphodiesterase (PDE) family of enzymes, which are key in regulating cAMP levels." (PMID 32508648, 2020). "PDE4D inhibitors have been used successfully as drug targets for asthma, such as theophylline since the 1930s and Ibudilast, an oral asthma drug approved in Asia." (PMID 32185106, 2020). "A study in an Icelandic cohort showed significant association with asthma and a SNP in IL1RL1 and SNPs in PDE4D have also shown association with genome-wide significance with asthma." (PMID 24066901, 2013). "PDE4D was identified as an asthma susceptibility gene, and PDE4 inhibitors have been developed as medications for asthma." (PMID 23829686, 2013). "Subsequent GWA studies of asthma identified variants in PDE4D and DENND1B associated with asthma at genome-wide significant levels, although the proposed variant in DENND1B showed considerable heterogeneity of associations between different populations." (PMID 23028483, 2012). "The primary findings of the PDE4D GWA study were obtained in a case-control design consisting of children from an asthma clinical trial and publicly available population controls." (PMID 20698975, 2010). "Notably, there are drugs targeting PDE4D, such as Cilomilast, developed for the treatment of respiratory disorders, such as asthma and COPD." (PMID 38730525, 2024). "Moreover, the indirect effects of MICB, PDE4D, and IL‐21 on childhood asthma via BMI are relatively modest, at 3.31%, 5.03%, and 3.43%, respectively." (PMID 38730525, 2024). "Consequently, a larger sample size is necessary to obtain additional support for investigating the role of PDE4D in asthma, specifically in the pediatric population." (PMID 38730525, 2024).